ARPC2 (actin related protein 2/3 complex subunit 2)
Description:
Actin-binding component of the Arp2/3 complex, a multiprotein complex that mediates actin polymerization upon stimulation by nucleation-promoting factor (NPF). The Arp2/3 complex mediates the formation of branched actin networks in the cytoplasm, providing the force for cell motility. Seems to contact the mother actin filament. In addition to its role in the cytoplasmic cytoskeleton, the Arp2/3 complex also promotes actin polymerization in the nucleus, thereby regulating gene transcription and repair of damaged DNA. The Arp2/3 complex promotes homologous recombination (HR) repair in response to DNA damage by promoting nuclear actin polymerization, leading to drive motility of double-strand breaks (DSBs).
Synonyms: p34-ARC; ARC34; PRO2446; PNAS-139
Tractability: Small molecule: a structure with a bound ligand is known. Antibody: its Gene Ontology location is reachable by antibodies, with medium confidence. PROTAC: ubiquitination databases record sites on it; its protein half-life has been measured.
Gene: Protein-coding gene on chromosome 2 (218,216,630 to 218,254,356, forward strand). Ensembl gene ENSG00000163466.
Subcellular location: Cytoplasm, cytoskeleton; Cell projection; Synapse, synaptosome; Nucleus
Subcellular location (Human Protein Atlas): Nucleoplasm
Pathways (Reactome):
Developmental Biology: EPHB-mediated forward signaling
Disease: FCGR3A-mediated phagocytosis
Immune System: Regulation of actin dynamics for phagocytic cup formation
Signal Transduction: RHO GTPases Activate WASPs and WAVEs
Vesicle-mediated transport: Clathrin-mediated endocytosis
Gene Ontology:
Molecular function: actin filament binding; protein binding; structural constituent of cytoskeleton; molecular adaptor activity
Biological process: Arp2/3 complex-mediated actin nucleation; positive regulation of lamellipodium assembly; actin cortical patch organization; actin filament polymerization; actin polymerization-dependent cell motility; positive regulation of cellular component biogenesis; positive regulation of cellular component organization
Cellular component: Arp2/3 protein complex; extracellular exosome; focal adhesion; lamellipodium; nucleoplasm; nucleus; actin cytoskeleton; cytoplasm; cytosol; site of double-strand break; cell leading edge; cytoskeleton; endosome; glutamatergic synapse; muscle cell projection membrane; plasma membrane; postsynapse; presynapse; synapse; synaptic vesicle membrane
Genetic constraint (gnomAD): Loss-of-function variants: 4 observed, 28.69 expected, observed/expected ratio (o/e) 0.14, 90% interval 0.068 to 0.32. The upper end of that interval is the gene's LOEUF score, 0.32, which puts it in group 1 of 6, group 1 being the genes least tolerant of losing a copy. Missense variants: 197 observed, 340.53 expected, observed/expected ratio (o/e) 0.58, 90% interval 0.51 to 0.65. Synonymous variants: 108 observed, 123.37 expected, observed/expected ratio (o/e) 0.88, 90% interval 0.75 to 1.03.
Homologues: Orthologues: dog ARPC2 (100% identical), guinea pig ARPC2 (99% identical), pig ARPC2 (99% identical), rat Arpc2 (99% identical), mouse Arpc2 (99% identical), macaque ARPC2 (99% identical), rabbit ARPC2 (98% identical), chimpanzee ARPC2 (97% identical), tropical clawed frog arpc2 (92% identical), zebrafish arpc2 (88% identical), Drosophila melanogaster Arpc2 (75% identical), Caenorhabditis elegans arx-4 (70% identical).
Diseases named in the same sentence as ARPC2 in open-access papers:
ARPC2 is named in the same sentence as 19 diseases in open-access papers, as found by Europe PMC text mining. Sharing a sentence is not in itself a finding about the gene and the disease. The quoted sentences say what the papers report.
breast carcinoma (11 papers, 2020 to 2024). "ARPC2 is involved in the control of intracellular dynamic changes of actin and facilitates cell migration and tumor metastasis in lung, colon, and breast cancer." (PMID 36404333, 2022). "ARPC2 promotes breast cancer proliferation and metastasis and is believed to be important for cell migration." (PMID 33976232, 2021). "RBM3 regulates ARPC2 in a post-transcriptional 3′UTR-binding manner to promote breast cancer cells proliferation and migration." (PMID 34804951, 2021). "In breast cancer, ARPC2 expression significantly upregulated the expression of vimentin, N-cadherin, MMP-9, ZEB1, and MMP-3, activated the TGF-β pathway, and eventually led to epithelial–mesenchymal transition (EMT)." (PMID 34307456, 2021). "ARPC2 plays a crucial role in actin polymerization and elevated expression thereof was correlated with unfavorable outcome for breast cancer patients." (PMID 32133296, 2020). "In the case of ARPC2 (a subunit of the Arp2/3 complex), a high level of the protein promoted breast cancer oncogenesis." (PMID 33036298, 2020). "The expression level of ARPC2 is higher in breast cancerous tissues than in adjacent noncancerous tissues, and ARPC2 is highly associated with the tumor stage and nodal metastasis in patients with breast cancer." (PMID 35733852, 2022). "ARPC2 expression is up-regulated in breast cancer, gastric cancer, and other tumor tissues, and the down-regulation of ARPC2 inhibits the invasion and migration of tumor cells, suggesting that it may be an oncogene." (PMID 35706452, 2022). "The results indicate that a high level of ARPC2 promotes EMT in breast cancer." (PMID 33036298, 2020). "In breast cancer, elevated HMMR activates AURKA and reduces ARPC2 localisation in the mitotic cell cortex, which correlates with micronucleation and the activation of cGAS-STING and non-canonical NF-κB signalling." (PMID 38633247, 2024). "A previous study reported that ARPC2 was closely associated with the stage, nodal metastasis, and overall survival in breast cancer and that the TGF-β/EMT pathway is involved in ARPC2-mediated carcinogenesis." (PMID 34307456, 2021). "Five of these antigens (VPS35, ARPC2, SERBP1, KRT8, and PDIA6) were selected because they inhibited human breast cancer survival across two aggressive breast cancer subtype cell lines (HER2 positive and triple negative)." (PMID 33976232, 2021).
gastric cancer (6 papers, 2017 to 2022). A primary or metastatic malignant neoplasm involving the stomach. "Clinically, an elevated ARPC2 level was associated with a lower survival rate in gastric cancer patients." (PMID 28694563, 2017). "For further study, we associated ARPC2 expression with clinic-pathological features from patients with gastric cancer." (PMID 28694563, 2017). "Furthermore, the expression of ARPC2 was associated with aggressive behaviors of gastric cancer, including large tumor size, lymph node invasion, high tumor stage, and poor prognosis." (PMID 28694563, 2017). "Herein, we confirmed for the first time that ARPC2 had adverse effects in human gastric cancer, and this was the first report on the role of ARPC2 in human cancers." (PMID 28694563, 2017). "As a result, ARPC2 played a destructive role in human gastric cancer cells and can be used as a potential target for the diagnosis and therapy of gastric cancer." (PMID 28694563, 2017). "In a clinical study, we examined the expression of ARPC2 in 110 cases of normal human gastric tissues and 110 cases of human gastric cancer tissues." (PMID 28694563, 2017). "In this study, we reported for the first time the destructive role of ARPC2 in human gastric cancer cells." (PMID 28694563, 2017). "In this study, we found that blocking ARPC2 by using the siRNA method can dramatically decrease the cell proliferation and invasion of the human gastric cancer cell line MKN-28." (PMID 28694563, 2017). "We thus identify that ARPC2 plays an aneretic role in human gastric cancer and provided a new target for gastric cancer therapy." (PMID 28694563, 2017). "We collected 110 normal gastric tissues and 110 gastric cancer tissues of archived formalin-fixed paraffin-embedded specimens and detected the protein level of ARPC2 using immunohistochemistry." (PMID 28694563, 2017). "A high expression of ARPC2 was associated with both poor RFS and OS rates in gastric cancer patients." (PMID 28694563, 2017). "In gastric cancer tissues, 40 of the 110 cases negatively expressed ARPC2 and 70 of the 110 cases positively expressed ARPC2; in normal gastric tissues, 70 of the 110 cases negatively expressed ARPC2 and 40 of the 110 cases positively expressed ARPC2." (PMID 28694563, 2017). "Previously, ARPC2 expression was found to be significantly elevated in gastric cancer tissues." (PMID 33971621, 2021). "Therefore, we propose ARPC2 as a new potential biomarker and therapeutic target for patients with gastric cancer." (PMID 28694563, 2017). "As a result, ARPC2 also promoted the invasion of human gastric cancer cells." (PMID 28694563, 2017). "ARPC2 showed higher expression in gastric cancer tissues than in normal gastric tissues." (PMID 28694563, 2017). "ARPC2 expressed higher levels in gastric cancer tissues than in normal gastric tissues." (PMID 28694563, 2017). "Furthermore, ARPC2 was significantly associated with large tumor size, lymph node invasion, and high tumor stage via association analysis of 110 gastric cancer tissues, and ARPC2-positive patients exhibited lower RFS and OS rates than ARPC2-negative patients with gastric cancer." (PMID 34307456, 2021). "Therefore, we may conclude that these genes might participate in the role that ARPC2 plays in promoting the cell proliferation and invasion of human gastric cancer cells." (PMID 28694563, 2017). "Therefore, ARPC2 promoted the proliferation of human gastric cancer cells." (PMID 28694563, 2017). "Moreover, CK636, the small molecule inhibitor of Arp2/3 complex which has been confirmed to participate in the process by which HOXA11 regulates the migration and invasion of gastric cancer cells, could also downregulate the expression of Arpc2 and Arpc3 which were upregulated by HOXA11." (PMID 31695791, 2019).
hepatocellular carcinoma (5 papers, 2022 to 2025). A malignant tumor that arises from hepatocytes. "ARPC2 was discovered to the abundantly expressed in hepatocellular carcinoma (HCC) and predicted unfavorable OS and progression-free survival of HCC." (PMID 36570337, 2022). "We also conducted differential expression analysis of ARPC2 in hepatocellular carcinoma (HCC) tissues and cell lines using qPCR, western blotting, and immunohistochemistry and explored its role in tumor proliferation, migration, and invasion of HCC cells." (PMID 35733852, 2022).
pancreatic cancer (3 papers, 2011 to 2022). "In various cancers, including breast, gastric, and pancreatic cancer, it has been indicated that ARPC2 is correlated with cancer proliferation and migration and a low survival rate of patients." (PMID 36558913, 2022). "Invasive pseudopods that we defined in these pancreatic cancer cells highly expressing ARL4C consisted of similar molecules, including cortactin, ARPC2, IQGAP1, and MMP14, which are involved in invadopodia functions." (PMID 34590580, 2021). "Meanwhile, components of invadopodia, such as cortactin and ARPC2, were localized at the tips of protrusions defined above, with ARL4C, suggesting that the protrusions might contribute to invasive phenotypes of pancreatic cancer cells and ARL4C functions there." (PMID 34590580, 2021).
Salmonella Infections (2 papers, 2018 to 2019). Infections with bacteria of the genus SALMONELLA. "On the other hand, FOXO signaling (TNFSF10, PRKAB1, GADD45B, STK4, STAT3), Salmonella infection (ARPC2, ARPC5L, CCL3L3, CCL4) and lysosome (LAPTM4B, HGSNAT, CD164, ATP6V0A2) pathways were up-regulated, albeit weakly, in the HLA-DR- Teff subset." (PMID 30231065, 2018).
abscess (1 paper, 2020). An inflammatory process characterized by the accumulation of pus within a newly formed tissue cavity which is the result of a bacterial, fungal, or parasitic infection or the presence of a foreign body. "Importantly, the number of recruited platelets and neutrophils, as well as neutrophil activation and abscess formation, was not affected by the loss of Arpc2 in platelets." (PMID 33188196, 2020).
breast tumor (1 paper, 2022). "ARPC2 increases breast tumor cell proliferation, migration, and invasion and activates the TGF-β pathway to contribute to epithelial-mesenchymal transition." (PMID 35733852, 2022).
E. coli infection (1 paper, 2021). "The expression of six genes (KRT18, ARPC5L, ACTG1, ARPC2, EZR, and YWHAZ) related to pathogenic E. coli infection was simultaneously increased with TNFRSF11B overexpression via gene set enrichment analysis (GSEA)." (PMID 34938284, 2021). "In addition, only six genes (KRT18, ARPC5L, ACTG1, ARPC2, EZR, and YWHAZ) related to pathogenic E. coli infection were simultaneously increased in both GSEA studies; these genes are mostly involved in focal adhesion, as determined via GO analysis." (PMID 34938284, 2021).
intrauterine growth restriction (1 paper, 2020). "Similarly, the Arp2/3 complex is important for early embryo development and preimplantation in pigs and mice, and ARPC2 transcripts are subject to RNA editing in placentas associated with intrauterine growth restriction/small for gestational age73." (PMID 32709900, 2020).
tumor (18 papers, 2017 to 2025). "Previous studies have reported that ARPC2 is overexpressed in various tumor tissues and is closely associated with prognosis." (PMID 35733852, 2022). "The ESTIMATE and CIBERSORT algorithms were used to evaluate the association between ARPC2 expression and the tumor microenvironment (TME) and immune infiltrating cells." (PMID 35733852, 2022). "Spearman correlation analysis was performed to investigate the relationship between ARPC2 expression and tumor mutational burden (TMB), DNA methyltransferases, microsatellite instability (MSI), immune-related genes, and mismatch repairs (MMRs)." (PMID 35733852, 2022). "In addition, we investigated the genetic alteration features of ARPC2 in various cancers, including the tumor mutational burden (TMB), DNA methylation, microsatellite instability (MSI), and mismatch repairs (MMRs)." (PMID 35733852, 2022). "Pearson’s correlation analysis demonstrated that the promoter methylation level of ARPC2 was negatively linked to ARPC2 expression in 27 tumor types, indicating that low DNA methylation might be one of the causes of high ARPC2 expression pan-cancer." (PMID 35733852, 2022). "A significant reduction in tumor growth was observed for each gene knockdown, with Arpc2 resulting in the strongest suppression." (PMID 40822358, 2025). "The subunit ARPC2 is a major structural component of the ARP2/3 complex and an elevated expression has been associated with metastasis, tumor size and lymph node invasion in other types of cancer." (PMID 37623256, 2023). "The results showed a close correlation between ARPC2 expression and the tumor stage in ACC, KIRC, KIRP, LIHC, and UCEC; the higher the ARPC2 expression levels, the higher the T or TNM stage." (PMID 35733852, 2022). "We extracted the mRNA expression of ARPC2 and analyzed the differential gene expression between the tumor and normal tissues using box plots." (PMID 35733852, 2022). "The top five tumor types whose immune cells were most positively or negatively correlated to ARPC2 expression were present in scatterplots." (PMID 35733852, 2022). "ARPC2 expression was significantly correlated with the tumor microenvironment (TME), infiltrating immune cells, TMB, microsatellite instability (MSI), and immune checkpoint-related genes in certain cancer types." (PMID 35733852, 2022). "Eight patients were randomly selected for western blot analysis, and the results indicated that ARPC2 expression was upregulated in HCC tumor tissues compared with that in adjacent normal liver tissues in seven of those samples." (PMID 35733852, 2022). "We discovered that the infiltration level of stromal cells and immune cells in the TME was positively correlated with ARPC2 expression in pan-cancer, whereas tumor purity showed the opposite results." (PMID 35733852, 2022). "This included downregulation of Arpc2, a regulator of actin polymerisation and mediator of tumour migration in several tissues." (PMID 35277659, 2022). "In conclusion, S-Benp is an active stereoisomer, and the biological activities of S-Benp occur by direct interaction with ARPC2 in cancer cells and tumor tissues." (PMID 36558913, 2022). "It was reported that ARPC2 inhibitors, such as benproperine and pimozide, inhibited tumor invasion and metastasis of cancer cells in animal models." (PMID 34307456, 2021). "Further study is warranted to investigate the potential function of chicken TRIM62 and ARPC2 on REV infection inducing tumor formation." (PMID 32318585, 2020). "For downstream genes, we found that cancer-promoting genes were upregulated while tumor suppress genes were downregulated by ARPC2." (PMID 28694563, 2017). "Focusing on Arpc2, we monitored overnight tumor cell movements from ex vivo midgut tracts." (PMID 40822358, 2025). "Moreover, ARPC2 inhibitors (benproperine and pimozide) can significantly suppress the migration and invasion of cancer cells and hamper tumor metastasis in animal models." (PMID 35733852, 2022).